WNK3 (WNK lysine deficient protein kinase 3)
Description:
Serine/threonine-protein kinase component of the WNK3-SPAK/OSR1 kinase cascade, which plays an important role in the regulation of electrolyte homeostasis and regulatory volume increase in response to hyperosmotic stress. WNK3 mediates regulatory volume increase in response to hyperosmotic stress by acting as a molecular crowding sensor, which senses cell shrinkage and mediates formation of a membraneless compartment by undergoing liquid-liquid phase separation. The membraneless compartment concentrates WNK3 with its substrates, OXSR1/OSR1 and STK39/SPAK, promoting WNK3-dependent phosphorylation and activation of downstream kinases OXSR1/OSR1 and STK39/SPAK. Following activation, OXSR1/OSR1 and STK39/SPAK catalyze phosphorylation of ion cotransporters SLC12A1/NKCC2, SLC12A2/NKCC1, SLC12A3/NCC, SLC12A4/KCC1, SLC12A5/KCC2 or SLC12A6/KCC3, regulating their activity. Phosphorylation of Na-K-Cl cotransporters SLC12A2/NKCC1 and SLC12A2/NKCC1 promote their activation and ion influx; simultaneously, phosphorylation of K-Cl cotransporters SLC12A4/KCC1, SLC12A5/KCC2 and SLC12A6/KCC3 inhibits its activity, blocking ion efflux. Phosphorylates WNK4, possibly regulating the activity of SLC12A3/NCC. May also phosphorylate NEDD4L. Also acts as a scaffold protein independently of its protein kinase activity: negatively regulates cell membrane localization of various transporters and channels, such as KCNJ1 and SLC26A9. Increases Ca(2+) influx mediated by TRPV5 and TRPV6 by enhancing their membrane expression level via a kinase-dependent pathway.
Synonyms: PRKWNK3; MRXS2; PRS
Tractability: Small molecule: a structure with a bound ligand is known; a high-quality ligand is known; it belongs to a druggable protein family. PROTAC: UniProt records ubiquitination sites on it; its protein half-life has been measured; a small molecule that binds it is known.
Target class: Kinase; Enzyme; Protein Kinase; Other protein kinase Wnk family; Other protein kinase group
Gene: Protein-coding gene on chromosome X (54,192,823 to 54,358,642, reverse strand). Ensembl gene ENSG00000196632.
Subcellular location: Cytoplasm
Subcellular location (Human Protein Atlas): Vesicles
Pathways (Reactome):
Transport of small molecules: Stimuli-sensing channels
Gene Ontology:
Molecular function: molecular condensate scaffold activity; protein binding; protein kinase activity; protein serine kinase activity; protein serine/threonine kinase activity; transmembrane transporter binding; transporter activator activity; ATP binding
Biological process: cell volume homeostasis; cellular hyperosmotic response; membraneless organelle assembly; monoatomic ion homeostasis; negative regulation of apoptotic process; negative regulation of protein localization to plasma membrane; osmosensory signaling pathway; positive regulation of calcium ion transport; positive regulation of peptidyl-threonine phosphorylation; positive regulation of protein localization to plasma membrane; positive regulation of sodium ion transmembrane transporter activity; positive regulation of sodium ion transport; protein localization to plasma membrane; regulation of calcium ion import; regulation of monoatomic cation transmembrane transport; renal sodium ion absorption; DNA damage response; intracellular signal transduction; maintenance of blood-brain barrier; positive regulation of canonical Wnt signaling pathway; protein phosphorylation; negative regulation of pancreatic juice secretion
Cellular component: cytoplasm; adherens junction; bicellular tight junction; cytosol
Homologues: Orthologues: chimpanzee WNK3 (98% identical), macaque WNK3 (97% identical), rabbit WNK3 (86% identical), guinea pig WNK3 (82% identical), pig WNK3 (80% identical), mouse Wnk3 (79% identical), rat Wnk3 (78% identical), tropical clawed frog wnk3 (56% identical), Drosophila melanogaster Wnk (25% identical), Caenorhabditis elegans wnk-1 (23% identical), zebrafish wnk3 (10% identical), Drosophila melanogaster Madm (8% identical), and 1 more. Paralogues in human: WNK1 (34% identical), WNK2 (33% identical), WNK4 (24% identical), NRBP1 (9% identical), NRBP2 (8% identical), DSTYK (8% identical).